IL2 (interleukin 2)
Diseases named in the same sentence as IL2 in open-access papers (continued):
Sharing a sentence is not in itself a finding about the gene and the disease.
kidney cancer (29 papers, 2004 to 2024). Primary or metastatic malignant neoplasm involving the kidney. "By contrast, high dose IL-2 that was used for treatment of melanoma and kidney cancer is associated with significant morbidity." (PMID 28443099, 2017). "A study on A498 kidney cancer cells found that survival signals promoted by IL-2 are mediated by SGK1 activation." (PMID 34249670, 2021). "In a small cohort of patients with skin and kidney cancer, stereotactic body radiotherapy with high dose IL2 showed better tumor response rates over that of IL2 alone." (PMID 30853982, 2019). "Then they were defined by activity when used as an irradiated vaccine, then by responding to high dose interleukin-2 (IL-2), as in kidney cancer." (PMID 28443099, 2017). "Cytokines have been used for more than a decade to treat kidney cancer: interleukin-2 (IL-2) and interferon-alpha with response rates of 10%-20%." (PMID 27974927, 2016). "Time interval from diagnosis (of kidney cancer) to start of HD IL2 of less than 12 months, lower Fuhrman grading both showed a possible link to response but this was not statistically significant." (PMID 27777776, 2016). "Other forms of therapy have been demonstrated to impact on orthotopic kidney cancer in mice, including the use of IL-2 in combination with anti-CD40 or IL-12 in the Renca system." (PMID 20426873, 2010). "To determine if memory was similarly invoked in mice bearing orthotopic kidney cancer following the inclusion of IL-2 in the treatment regimen, we rechallenged surviving mice with Renca (2 × 105, subcutaneously)." (PMID 20426873, 2010). "Core needle biopsies of metastatic and/or the primary kidney cancer were obtained before interleukin-2 (IL-2)- and IFN-α-based immunotherapy in 34 patients and repeated after 5 weeks in 25 patients." (PMID 14760375, 2004). "SGK1 was also demonstrated to be a downstream effector of interleukin-2 (IL-2) in kidney cancer." (PMID 33542904, 2020). "IL-2 is known to exert anti-proliferative and pro-apoptotic effects on kidney cancer cells." (PMID 27561007, 2016). "In kidney cancer, the NK cell within tumor only was activated by IL-2 stimulation could have the target cell solution function." (PMID 25299645, 2014). "Interleukin-2 (IL-2) or aldesleukin is used to treat skin melanomas and kidney cancer." (PMID 21686188, 2011). "Since CD8+ T cells were previously demonstrated to play a crucial role in Tri-mAb therapy, we reasoned that coadministration of the T cell growth factor, IL-2, may enhance Tri-mAb therapy of orthotopic kidney cancer." (PMID 20426873, 2010). "Similarly, immunotherapies are effective in kidney cancer, including high-dose interleukin 2 and checkpoint inhibitors, but the latter may be too recent to impact the data reported here (nivolumab was approved in 2015, followed by many others)." (PMID 37345119, 2023). "Over the last decade, new targeted therapies were introduced for systemic therapy of kidney cancer and largely replaced therapies with interferon-alpha (INF-α) or interleukin-2 (IL-2)." (PMID 29108248, 2017). "In previous reports, a correlation between baseline NLR and survival was shown in kidney cancer and NSCLC treated with IL-2 and nivolumab, respectively." (PMID 29318140, 2017). "In experiments described herein, we found that orthotopic kidney cancer was indeed much more difficult to treat than subcutaneous disease, but response rates of mice bearing orthotopic disease could be significantly raised (to ~55%) by the addition of high dose IL-2 to the treatment regimen." (PMID 20426873, 2010). "We did not observe any “Lazarus effect” even if patients with kidney cancer were included, and IL-2 is a recognized treatment for this disease." (PMID 33800511, 2021).
lupus nephritis (28 papers, 2014 to 2025). Glomerulonephritis in the context of systemic lupus erythematosus. "In conclusion, using a Bayesian network meta-analysis encompassing nine RCTs, we found that low-dose IL-2 was the most effective biological therapy for patients with lupus nephritis and had the best chance of lowering the risk of SAE." (PMID 36327917, 2023). "Interestingly, IL-23 receptor-deficient MRL/lpr mice displayed attenuated lupus nephritis associated with an increased expression of IL-2 while IL-17 was reduced." (PMID 33496881, 2021). "Low dose IL-2, for in vivo expansion of Tregs, showed improved response rates compared to placebo in patients with refractory lupus nephritis in 2 RCTs." (PMID 39278988, 2025). "Our results suggest that the combination of IL-2 and a calcineurin inhibitor exerts an additive effect in the treatment of lupus nephritis." (PMID 38665907, 2024). "Another single-center, open-label clinical study used three cycles of low-dose IL-2 in addition to standard-of-care therapy in eighteen patients with active lupus nephritis." (PMID 37781677, 2023). "Higher complete remission rates along with a more favorable safety profile indicate that low-dose IL-2, obinutuzumab, rituximab, and belimumab are better therapies for lupus nephritis than other treatments." (PMID 36327917, 2023). "Our data showed that low-dose IL-2 was the most effective therapy for lupus nephritis, followed by obinutuzumab, rituximab, and belimumab, all of which outperformed the control." (PMID 36327917, 2023). "Low-dose IL-2 was the most effective induction treatment for patients with lupus nephritis and had the lowest potential for SAE." (PMID 36327917, 2023). "In the IL-2 group, patients with lupus nephritis had a complete remission rate of 53.85% compared to 16.67% in the placebo group." (PMID 37771588, 2023). "In patients with lupus nephritis, low-dose IL-2 therapy resulted in complete remission in 53.85% (7/13) of cases compared with only 16.67% (2/12) in the placebo group (p = 0.036)." (PMID 36327917, 2023). "Rapamycin treatment alleviated SLE-like experimental lupus nephritis by the recovery of IL-2 production, which modulated the maintenance and expansion of CD4+FOXP3+ Tregs, in turn inhibiting activated effector T cells." (PMID 36979928, 2023). "Complementing these clinical trials, the efficacy of low-dose IL-2 in patients with lupus nephritis was investigated in a single-center, controlled phase I/IIa trial." (PMID 33868284, 2021). "For example, the number of Tregs is reduced in patients with lupus nephritis due to impaired T cell-mediated IL-2 production." (PMID 33496881, 2021). "During disease progression of lupus nephritis, a higher expression of inhibitory receptor PD-1 was associated with a lower degree of CD4+ Tmem-cell functionality regarding IL-2, TNF-α and IFN-γ expression." (PMID 32441253, 2020). "Furthermore, the complete remission rate of low-dose IL-2-treated lupus nephritis patients was also significantly higher at both weeks 12 and 24, while IL-2-treated individuals had reduced 24-hour proteinuria in contrast to the placebo group." (PMID 38558805, 2024). "Addition of calcineurin inhibitors as adjunct agents may be beneficial for IL-2-based treatment of lupus nephritis." (PMID 38665907, 2024). "The regulation of Tfh production using a combination of a calcineurin inhibitor and IL-2 may be a logically appropriate therapeutic strategy for lupus nephritis." (PMID 38665907, 2024). "We investigated whether combination treatment with a calcineurin inhibitor (tacrolimus) and IL-2 can selectively induce Treg expansion while inhibiting Tfh expansion, exerting an additive treatment effect against lupus nephritis-like symptoms." (PMID 38665907, 2024). "An open-label controlled trial in lupus nephritis.IL-2 + SOC (n=18).SOC (n=12)." (PMID 37771588, 2023).
lupus nephritis (continued). "Higher complete remission rates and a more favorable safety profile suggest that low-dose IL-2, obinutuzumab, rituximab, and belimumab may be superior to the current control as treatments for lupus nephritis." (PMID 36327917, 2023). "Thus, we propose that rapamycin treatment favored the Tregs population and IL-2 augmentation further expanded Tregs in vivo, thus ameliorating lupus nephritis by suppressing activated effector cells." (PMID 36979928, 2023). "Our meta-analysis also indicated that the MSC treatment group also had lower levels of IL-2, IL-12, IL-17, and IFN-γ when compared with the control group in lupus nephritis mice." (PMID 32019582, 2020). "Proinflammatory chemokines (MCP-1) and cytokines (IL-6, TNF-α), Th1 cytokines (IL-2, IFN-γ), Th2 cytokines (IL-4, IL-10), and Th17 cytokines (IL-17A) are involved in pathogenesis of lupus nephritis, and are therapeutic targets for lupus nephritis." (PMID 27846813, 2016). "The Korean study testing haploidentical allogeneic BM-MSCs has progressed to a phase 2 trial for refractory lupus nephritis (NCT04835883), while a phase 3 RCT in China is comparing UC-MSC against low dose IL-2 as an add-on therapy to SOC immunosuppression (NCT05631717)." (PMID 39278988, 2025). "The IL-2 group had early significantly higher proportions of SRI-4 responders than the placebo group and up to week 24 (29% difference) and 54% of the patients in a subgroup with lupus nephritis had a complete renal response at week 12 vs. 8% in the placebo group." (PMID 37781677, 2023). "Positive effects in patients with refractory lupus nephritis were also seen in another study that reported a dramatic reduction of proteinuria, of urine erythrocytes, and anti-dsDNA antibodies after starting low-dose IL-2 therapy, with no flares during the second year of IL-2 maintenance therapy." (PMID 37781677, 2023).
pulmonary edema (28 papers, 1995 to 2025). Accumulation of fluid in the lung tissues causing disturbance of the gas exchange that may lead to respiratory failure. "IL-2 treatment is often associated with toxic side effects, which have limited its therapeutic use except at low doses e.g., inducing vascular leak syndrome, hypotension, pulmonary oedema, liver cell damage, and decreased blood oxygen saturation." (PMID 37317296, 2023). "Pulmonary edema is caused by direct binding of IL-2 with the functional form of IL-2 receptors (IL-2Rαβγc) on lung endothelial cells and blocking the a-chain leads to dramatically reduction of the pulmonary toxicity induced by IL-2." (PMID 35213635, 2022). "High-dose IL-2 is also associated with significant toxicity including neurological symptoms and a systemic capillary leak syndrome that can result in significant hypotension, renal failure, and pulmonary edema requiring intensive care unit (ICU) care." (PMID 30747243, 2019). "Taken together, these results suggest a broad correlation between the magnitude of immune cell expansion and the development of treatment-associated toxicities, with low-dose IL-2/mAb or IL-23XFc treatments displaying higher levels of toxicity, particularly pulmonary oedema, compared to IL-2WTFc." (PMID 28497796, 2017). "Mimicking the alveolar-capillary interface and subjected to fluid flow and cyclic mechanical strain, the microdevice successfully reproduces the pulmonary edema found in cancer patients undergoing interleukin-2 (IL-2) treatment." (PMID 39996978, 2025). "Later, Interleukin-2 (IL-2) and angiopoietin-1 (Ang-1) were sequentially introduced into this model to replicate the pathophysiology of pulmonary edema." (PMID 40528968, 2025). "Through real-time imaging and quantitative analysis facilitated by the integrated optical sensors, the study unveils the critical role of physiological breathing motions that exacerbate IL-2 toxicity, resulting in pulmonary edema." (PMID 39996978, 2025). "This pulmonary-edema-on-a-chip reproduced lung function in response to interleukin-2 (IL-2), and also successfully screened a drug for pulmonary edema." (PMID 34821672, 2021). "A life-threatening side effect of prescribing Proleukin®/IL-2 to patients is the development of pulmonary edema." (PMID 33193321, 2020). "This produced a pathological model of pulmonary edema through the introduction of interleukin-2 (IL-2)." (PMID 32050989, 2020). "Treatment with IL-2/mAb or IL-23XFc induced pulmonary oedema, as evidenced by increases in lung water content." (PMID 28497796, 2017). "Using their breathing chip design, Huh and colleagues were able to recreate interleukin-2 (IL-2) induced vascular leakage that eventually leads to pulmonary edema." (PMID 28953246, 2017). "Consistent with in vivo IL-2-induced pulmonary edema, the human lung-on-a-chip system successfully showed vascular leakage and flow into the epithelial-sided air channel in response to IL-2 treatment regardless of added mechanical stress." (PMID 23335897, 2012). "Next, the authors checked if the IL-2-induced pulmonary edema-on-a-chip model is applicable to testing pharmacological agents." (PMID 23335897, 2012). "After the first round of therapies, addition of L-NAME significantly reduced IL-2-induced pulmonary oedema and water retention in the spleen in a dose-dependent manner." (PMID 8546905, 1996). "High-dose IL-2 regimens are limited by side-effects such as pulmonary oedema and a systemic vascular leak." (PMID 7819054, 1995). "Endothelial lung cells have also been shown to express IL-2R on their surface and that IL-2 could bind to endothelial cells and induce pulmonary edema in response to this link." (PMID 34001199, 2021).
pulmonary edema (continued). "The majority of the toxicities directly attributable to IL-2 were grade 1 or 2 and were those relating to vascular leak syndrome, including peripheral edema, pulmonary edema, hypotension and increased creatinine or decreased urine output, as well as fever, fatigue and neurological symptoms." (PMID 30747243, 2019). "However, IL-2 concomitantly acts on Tregs that suppress anti-tumor responses, and systemic IL-2 injections had severe adverse effects including vascular leak syndrome and pulmonary edema due to IL-2Rα expression on endothelial cells." (PMID 31766350, 2019). "Moreover, upregulation of the PI3K-Akt signaling pathway promotes expression of IL2, FGF2, and VEGFA, which aggravates inflammation, induces epithelial cell apoptosis, and increases vascular permeability and pulmonary edema." (PMID 33746744, 2020). "Pulmonary edema, the most serious side effect of IL-2 therapy, was not exacerbated by IL-2C treatment." (PMID 26772545, 2016). "Furthermore, unlike IL-23XFc and IL-2/mAb treatment, IL-2WTFc did not induce pulmonary oedema or reductions in body weight." (PMID 28497796, 2017). "Ginseng could reduce the pathologic damage, neutrophil aggregation, proinflammatory factors, and pulmonary edema in vivo and inhibit the PI3K-Akt signaling pathway and MAPK signaling pathway through downregulating expressions of STAT3, VEGFA, FGF2, PIK3CA, MAPK1, and IL2." (PMID 33746744, 2020).
Thrombocytopenia (28 papers, 2003 to 2025). A reduction in the number of circulating thrombocytes. "While the direct influence of IL-2 on platelets remains elusive, preliminary investigations have reported adverse outcomes such as thrombocytopenia with increased viability of residual platelets with moderate and high-dose IL-2 treatment in cancer patients." (PMID 38256942, 2024). "The cytokine storm is a major driver of the IL-2-mediated side effects, some of which include fever, chills, malaise, diarrhea, nausea, anemia, thrombocytopenia, eosinophilia, elevation of hepatic enzymes, and confusion." (PMID 34553029, 2021). "Our observations suggest a relationship between degree of thrombocytopenia and clinical response to IL-2 treatment." (PMID 25815245, 2015). "One group studied the bone marrows of IL-2 patients who developed thrombocytopenia and found normal numbers and morphology of megakaryocytes." (PMID 31546315, 2014). "They attributed the thrombocytopenia to sequestration in the spleen due to IL-2-induced splenomegaly (JPD, personal observation)." (PMID 31546315, 2014). "A major group of genes (GMCSF, RANTES, IL2, INFγ, TLR6, CCR2A, IL-6, CKR-4) causing thrombocytopenia and vascular permeability was also found to be up-regulated in all three cell types." (PMID 19117515, 2008). "Previous reports have demonstrated the efficacy of cyclosporine for thrombocytopenia in TAFRO syndrome, suggesting that inhibition of IL-2 may improve thrombocytopenia." (PMID 38872134, 2024). "The reduction of IL-2 and IL-12 associated with PDW may be consistent with regulation of immune response which is associated with appearance of mega platelets in thrombocytopenia caused by vivax malaria." (PMID 32696915, 2020). "The linear regression showed that the levels of IL-1β, IL-2 and IL-12 were associated with altered PDW in Pv-MAL patients, and they may be predictors of the medullar response to thrombocytopenia caused by vivax malaria." (PMID 32696915, 2020). "Our data demonstrate that an increase in MPV and the association between reductions of IL-2 and IL-12 and PDW values may be an immune response to thrombocytopenia in uncomplicated P. vivax malaria." (PMID 32696915, 2020). "The precise mechanism of development of marked thrombocytopenia in association with response to IL-2 has not been conclusively elucidated." (PMID 25815245, 2015). "Others have reported that thrombocytopenia correlates with response to high-dose IL-2." (PMID 24855563, 2014). "IL-2, TNF-α, VEGF-D, and IL-6 were correlated with thrombocytopenia and these markers were valuable for predicting bleeding." (PMID 35631079, 2022). "Severe thrombocytopenia was positively correlated with IL-4, CXCL10, IL-6, IL-10 and IFN-γ levels, renal dysfunction was related to an increase in IL-2, IL-1β, IL-17A and IL-8, and hepatic impairment with CXCL10, MCP-1, IL-6 and IFN-γ." (PMID 36178979, 2022). "We identified significant correlations between serum IL-2, IL-6, TNF-α, and VEGF-D levels and thrombocytopenia in DENV-infected patients in the present study, consistent with the findings of other reports." (PMID 35631079, 2022). "Thrombocytopenia was the dose-limiting toxicity (DLT) of TMZ and combined subcutaneous immunotherapy with low-dose IL2, GM-CSF and IFNα, and it was dose- and patient-dependent." (PMID 12610499, 2003). "The various stages of infection are characterized by high levels of inflammatory markers such as CRP, interleukins (IL-2, IL-6, IL-7), LDH, ferritin, lymphocytopenia, thrombocytopenia, leukopenia, elevated procalcitonin, D-dimer, prothrombin, fibrinogen, and others." (PMID 36982882, 2023). "The observed adverse events were described previously and are known to be attributable to IL-2 and not TILs: asthenia for 6, anorexia for 3, myalgias for 2, nausea for 2, and, for 1 each thrombocytopenia, vomiting, ageusia, pruritus, cutaneous rash, flu-like syndrome, or chills." (PMID 29750176, 2018).